HPSE (heparanase)
Diseases named in the same sentence as HPSE in open-access papers (continued):
Sharing a sentence is not in itself a finding about the gene and the disease.
myeloma (continued). "In summary, we have identified a mechanism by which HPSE expression in myeloma and endothelial cells leads to activation of VEGFR2 and an invasive phenotype." (PMID 26926788, 2016). "Probing a role for heparanase in myeloma resistance we found that heparanase, by maintaining high levels of active ERK in tumor cells, promotes tumor survival that drives resistance in response to therapy." (PMID 26624982, 2016). "Heparanase is present in the bone marrow of most myeloma patients where high levels of heparanase enzyme activity correlates with elevated angiogenic activity, an important promoter of myeloma growth and progression." (PMID 26624982, 2016). "It is present in the nucleus of myeloma cells, and amount of nuclear syndecan-1 is reduced upon elevation of heparanase expression." (PMID 26420915, 2015). "Results of in vivo studies showed that SST0001 effectively inhibited myeloma growth and diminished heparanase-induced shedding of SDC1." (PMID 26293675, 2015). "Our results suggest that FGF23 from skeletal osteocytes drives a vicious cycle of myeloma growth in bone by binding to MM cells and activating transcription of pro-metastatic and pro-osteolytic genes, such as heparanase." (PMID 25944690, 2015). "It is also documented that heparanase initiates the growth of myeloma cells and promotes bone metastasis by increasing the size of blood vessels within the tumor." (PMID 24551591, 2014). "Roneparstat also diminishes heparanase-induced shedding of syndecan-1, which is known to be a potent promoter of myeloma growth." (PMID 25105093, 2014). "The antitumor action of chemically modified heparins has been shown to inhibit myeloma growth and angiogenesis via disruption of the heparanase/syndecan-1 axis, and our data strongly confirm the usefulness of this therapeutic approach." (PMID 25386176, 2014). "Upregulation of heparanase expression or exogenous addition of recombinant heparanase to myeloma cells stimulates SDC-1 expression and shedding." (PMID 24551591, 2014). "Another possible mechanism for the pro-tumorigenic effects of heparanase in myeloma was recently elucidated in animal models, which revealed that heparanase enhances myeloma progression via CXCL10 downregulation." (PMID 25105093, 2014). "These factors can be liberated by heparanase, produced by the bone marrow microenvironment as well as some myeloma cell samples, which cleaves heparan sulfate chains from proteoheparan sulfates." (PMID 24386263, 2013). "“Squeezing” this sponge by shedding of the heparan-sulfates from the syndecan-1 core protein, e.g. by heparanase produced by myeloma cells or the bone marrow environment, can liberate these growth factors and promotes angiogenesis." (PMID 24386263, 2013). "On the other hand, SST0001 is an N-acetylated, glycol-split high molecular weight heparin that also exhibits low anticoagulant activity, selectively inhibits heparanase and has shown activity in an in vivo model of multiple myeloma." (PMID 21698156, 2011). "We have demonstrated the effectiveness of glycol-split heparinoids, including compound HI-2 (=100NA,R.OH), in suppressing the biological activity of heparanase, applying in-vivo models of inflammation, melanoma lung colonization,86 and myeloma tumor growth." (PMID 23908791, 2011). "By confocal microscopy, western blotting and ELISA assay we demonstrate that when heparanase expression is increased in a human myeloma cell line, the level of syndecan-1 in the nucleus decreases dramatically." (PMID 19305494, 2009). "Upon upregulation of heparanase expression or following addition of recombinant heparanase to myeloma cells, the nuclear localization of syndecan-1 drops dramatically as revealed by confocal microscopy, western blotting and quantification by ELISA." (PMID 19305494, 2009). "Syndecan-1 is particularly abundant in multiple myeloma, where an emerging role for heparanase has recently been shown." (PMID 18545691, 2008).
myeloma (continued). "The mechanism of action of HPSE has been revealed in multiple myeloma." (PMID 41301515, 2025). "Furthermore, heparanase‐enhanced shedding of SDC1 by myeloma cells has been shown to promote endothelial invasion and angiogenesis." (PMID 41039734, 2025). "Moreover, heparanase-dependent activation of the ERK and p38 signaling pathways is associated with myeloma progression." (PMID 36980254, 2023). "In addition, heparanase is an important factor in the biogenesis and functioning of exosomes, which influence the control of cell behavior in the myeloma microenvironment and distal sites." (PMID 36980254, 2023). "The endoglycosidase, heparanase, has also been reported to promote myeloma stemness." (PMID 37568580, 2023). "Importantly, the EVs secreted by the myeloma cells have high levels of HPSE as cargo and blocking HPSE enzyme activity with antibody H1023 inhibits this EV‐mediated invasion by macrophages." (PMID 37091070, 2023). "Furthermore, anti-myeloma chemotherapy evokes secretion of exosomes enriched in heparanase that remodel the tumour stroma and contribute to chemoresistance and patient relapse." (PMID 34982945, 2022). "Heparanase upregulation in the setting of anti-myeloma therapy may serve as markers of chemoresistance and eventual relapse." (PMID 35118073, 2021). "Furthermore, the interaction of multiple myeloma cells with microvascular endothelial cells increased expression of heparanase, vascular endothelial growth factor, ICAM-1, and E-selectin in endothelial cells; defibrotide suppressed these effects." (PMID 34584241, 2021). "Thus, anti-myeloma chemotherapeutic agents, including bortezomib (proteasome inhibitor) or melphalan (alkylating agent), were shown to increase the expression and secretion of heparanase in an in vitro myeloma model." (PMID 33800172, 2021). "This brings into focus the protumorigenic role of heparanase in myeloma and other tumors." (PMID 34778093, 2021). "However, in the same study, defibrotide inhibited heparanase activity in multiple myeloma cells and, while adding exogenous heparanase increased the invasion potential of multiple myeloma cells, defibrotide treatment abolished this effect." (PMID 34584241, 2021). "Indeed, heparanase has been shown to enter the nucleus of myeloma cells and cleave nuclear HS on syndecan-1." (PMID 34681753, 2021). "To further probe the impact of heparanase on PTEN in myeloma cells, we examined whether heparanase alters the phosphorylation state of PTEN." (PMID 32899927, 2020). "Production of heparanase increases motility of myeloma cells and induces a migratory phenotype." (PMID 33634031, 2020). "In the present work, we investigated the role of nuclear heparanase in regulating myeloma behavior." (PMID 32899927, 2020). "Another strategy uses heparanase-neutralizing monoclonal antibodies to target the interaction of heparanase with HS and has been tested in pre-clinical studies for various types of cancer, including myeloma, pancreatic carcinoma, and hepatocellular carcinoma." (PMID 31963505, 2020). "HPSE inhibition is not expected to cause direct tumor cell kill, and, as expected, this study did not provide evidence of a potential direct anti-myeloma effect of ronepartstat in humans." (PMID 32957513, 2020). "In fact, stimulation of Sdc1 shedding by heparanase enhances Met signaling in myeloma cells." (PMID 32453780, 2020). "The enzymatic activity of heparanase is well studied in multiple myeloma." (PMID 32494847, 2020). "Human embryonic kidney cells and myeloma cells overexpressing T5, or heparanase, displayed enhanced Src phosphorylation, whereas Erk (extracellular signal regulated kinase) phosphorylation was not affected, and in the case of T5 this effect was independent of HS." (PMID 31850210, 2019). "Indeed, gene expression analyses of myeloma cells from patients subjected to sequential rounds of chemotherapy revealed that tumor cells that survived expressed elevated levels of heparanase." (PMID 30413079, 2018).
myeloma (continued). "Based on this clinical data, we hypothesized that heparanase was involved in myeloma resistance to drug therapy." (PMID 26624982, 2016). "Because our data indicate that heparanase promotes drug resistance of myeloma cells, we tested whether blocking heparanase enzyme activity using heparanase inhibitor, Roneparstat (Rone) would sensitize myeloma cells to chemotherapy." (PMID 26624982, 2016). "The present study demonstrates that heparanase promotes drug resistance and relapse in myeloma." (PMID 26624982, 2016). "In the present study, gene expression profiling of tumor cells isolated from myeloma patients after sequential rounds of chemotherapy, revealed for the first time that heparanase, a potent promoter of myeloma growth and progression, was elevated in myeloma cells that survived therapy." (PMID 26624982, 2016). "Furthermore, heparanase was shown to be present at a high level on tumour cells that survive extensive chemotherapy in myeloma patients, lending further support to the notion that heparanase promotes resistance to therapy." (PMID 27408707, 2016). "High levels of heparanase (HPSE) correlate with poor prognosis in myeloma patients." (PMID 26926788, 2016). "Heparanase accelerates MMP-9 mediated shedding of syndecan-1 in both myeloma and breast cancer." (PMID 26420915, 2015). "The mechanism of heparanase aggressive phenotype priming is in part due to synergy with the heparan sulfate proteoglycan syndecan-1 to create a niche within the bone marrow microenvironment, further driving myeloma growth and dissemination." (PMID 25386176, 2014). "Similarly, heparanase has been demonstrated to regulate the expression of syndecan-1 in multiple myeloma cells." (PMID 25105093, 2014). "Thus, antibody 7c4 reacted similarly with tumor xenografts generated by CAG human myeloma cells over-expressing heparanase or T5 (left)." (PMID 23251556, 2012). "A novel mechanistic pathway driven by heparanase expression in myeloma cells can induce elevated levels of VEGF and shedding of syndecan-1 from matrix-anchored complexes that together activate integrin and VEGF receptors on adjacent endothelial cells, thereby stimulating tumor angiogenesis." (PMID 22773903, 2012). "Using confocal microscopy we noted that syndecan-1 was localized within the nucleus of CAG myeloma cells expressing low levels of heparanase (HPSE-low cells) but it not present within the nucleus of CAG cells expressing high levels of heparanase (HPSE-high cells)." (PMID 19305494, 2009). "To determine whether one such mechanism is related to heparanase presence and activity in the nucleus, we first assessed whether myeloma patients in the HPSE-high group (from the MMRF CoMMpass database) had elevated PTEN as compared to patients in the HPSE-low group." (PMID 32899927, 2020). "Employing the Multiple Myeloma Research Foundation CoMMpass database, we demonstrate that patients expressing high levels of heparanase display elevated expression of proteins involved in chromatin remodeling and several oncogenic factors compared to patients expressing low levels of heparanase." (PMID 32899927, 2020). "In myeloma, re-expressing wild-type PTEN in PTEN-deficient cells represses proliferation and invasion by downregulating FAK, MMP2 and MMP9 expression and activity, indicating that HPSE and PTEN are targeting expression of the same proteins but in opposite ways." (PMID 32899927, 2020). "Moreover, the forced high expression of heparanase in myeloma cells induced chemoresistance." (PMID 30413079, 2018). "Our data also point to the potential use of heparanase inhibitors like Roneparstat for targeting minimal residual disease (MRD) in myeloma patients, the idea being that inhibition of heparanase might interfere with reestablishment of a microenvironment, thereby preventing relapse." (PMID 26624982, 2016). "In addition, heparanase seems to play a distinct role in the shedding of SDCs in myeloma." (PMID 24551591, 2014).
myeloma (continued). "Heparanase (HPSE) plays an important role in supporting and promoting myeloma progression, maintenance of plasma cell stemness, and resistance to therapy." (PMID 36980254, 2023). "Treatment with bortezomib and melphalan induces secretion of exosomes containing heparanase that results in degradation of ECM; thus, facilitating myeloma invasion." (PMID 35847862, 2022). "MM cells with high heparanase expression have been reported to shift the differentiation potential of OB progenitors to adipogenesis; mechanistically, this shift was due to heparanase-enhanced production of DKK1 by both OB progenitors and myeloma cells." (PMID 34067236, 2021). "Again, heparanase has been shown to enhance ERK phosphorylation levels in macrophages and myeloma cell lines through its enzymatic activity." (PMID 34681753, 2021). "Commonly used chemotherapy and radiation regimens promote heparanase upregulation and increase SDC-1 shedding in malignancies such as myeloma, pancreatic cancer and medulloblastoma." (PMID 35118073, 2021). "Myeloma cells exposed to elevated heparanase levels exhibited increased secretion of exosomes containing SDC-1 and heparanase." (PMID 35118073, 2021). "HPSE has been reported to enhance the expression of the EMT markers vimentin, fibronectin and RANK in multiple myeloma cells and consequently their motility, partly due to activation of the ERK signaling pathway." (PMID 33809973, 2021). "The human multiple myeloma RPMI8226 and the lymphoma SUDHL4 xenografts, which express heparanase showed low sensitivity to the HDAC inhibitor alone." (PMID 34857011, 2021). "To verify our heparanase ChIP assay specificity, we probed the promoter region of the RUNX2 gene, known to promote myeloma progression." (PMID 32899927, 2020). "Myeloma cells also facilitate degradation of the ECM using matrix metalloproteinases (MMP) and heparanase to allow migration of endothelial cells into the surrounding tissue." (PMID 33634031, 2020). "NK and T-cells express Sdc1, VEGFR2, CXCR4, AC7 and HPSE and their LFA-1-mediated migration in in vitro invasion assays is dramatically increased by SSTNVEGFR2 while at the same time the peptide inhibits the VLA-4-mediated invasion of myeloma cells." (PMID 34778093, 2021). "Furthermore, heparanase and Hpa2 supported the adhesion of RPMI8266 and U266 myeloma cells that normally grow in suspension, and this was similarly abrogated by heparin, suggesting that the pro-adhesive properties of Hpa2 are mediated primarily by HS." (PMID 33585253, 2020). "OGT2115 is a small molecule inhibitor, but in the myeloma cells, it is not known whether it is blocking heparanase activity within the cytoplasm and inhibiting transport to the nucleus, or it is present in the nucleus, where it could block heparanase activity resulting in loss of nuclear heparanase." (PMID 32899927, 2020). "Additionally, heparanase stimulates the expression of MMP-9 via ERK signaling, promoting shedding of syndecan-1 proteoglycan (CD138) from the myeloma cell surface." (PMID 31963505, 2020). "This compound was shown to inhibit tumor growth and metastasis in a mouse xenograft model with human myeloma cells, but no other activities described for heparanase were examined." (PMID 31850210, 2019). "Myeloma cells from three different cell lines (CAG HPSE-high, U266 and MM1.S) were treated with different chemotherapeutic agents for 14 h either alone or following 6 h pretreatment with heparanase inhibitor, Roneparstat (Rone, 6.75 μM)." (PMID 26624982, 2016). "Despite this clear evidence that heparanase is an important driver of myeloma progression, a role for heparanase in myeloma drug resistance has not been addressed." (PMID 26624982, 2016). "Heparanase, by elevating the expression and activity of growth factors (HGF, VEGF), proteases (MMP-9, uPA) and RANKL, primes the tumor microenvironment to favor myeloma growth and dissemination." (PMID 26624982, 2016).
myeloma (continued). "Co-regulation of heparanase and MMP-9 expression was recently demonstrated in myeloma cells." (PMID 19360105, 2009). "The present study indicates the mutual role of HPSE and HPSE2 regulatory elements in the manifestation of multiple myeloma and proposes the use of heparanase 2-mimicking drugs for a most pronounced suppression of heparanase activity in multiple myeloma accompanied by EMD and osteolytic bone disease." (PMID 36980254, 2023). "Furthermore, the ability of roneparstat to inhibit multiple myeloma growth and angiogenesis has been correlated with disruption of the heparanase/syndecan-1 axis and downregulation of HGF, VEGF and MMP-9 gene expression controlled by endogenous heparanase in myeloma cells." (PMID 27374103, 2016). "In this system, however, transfection of heparanase into myeloma cells, or addition of recombinant active heparanase enhanced their expression of pro MMP-9 in vitro and knockdown of heparanase expression in wt myeloma cells reduced the level of MMP-9 expression." (PMID 19360105, 2009). "Likewise, the heparanase inhibitor Roneparstat (formerly SST0001) in combination with a proteasome inhibitor (bortezomid) or melphalan was found to be an effective therapeutic strategy to inhibit disseminated tumor growth and overcome drug resistance in myeloma bearing mice." (PMID 29721203, 2018). "Heparanase induction of HGF and C–X–C motif chemokine ligand 10 (CXCL10) in multiple myeloma appears not to rely on the endo-β-d-glucuronidase enzymatic activity." (PMID 30413079, 2018). "Heparanase induces SDC1 shedding, and soluble SDC1 is an independent negative prognostic factor in multiple myeloma." (PMID 26293675, 2015).